ANXA1 (annexin A1)
Diseases named in the same sentence as ANXA1 in open-access papers (continued):
Sharing a sentence is not in itself a finding about the gene and the disease.
prostate carcinoma (continued). "Addressing these limitations through future research endeavours will improve the understanding of the role of RRM2, ANXA1, and the PI3K/AKT pathway in therapeutic resistance in prostate cancer and facilitate the development of more effective treatment strategies." (PMID 37968699, 2023). "Targeting RRM2, ANXA1, or the PI3K/AKT pathway may offer promising therapeutic strategies to overcome docetaxel resistance in prostate cancer." (PMID 37968699, 2023). "To substantiate the hypothesis that RRM2 influences ANXA1 content in PCa cells, we meticulously examined the protein and mRNA levels of ANXA1 following RRM2 knockdown in prostate cancer cells." (PMID 37968699, 2023). "Our result demonstrated that Annexin A1 served as a downstream target for TRPM7-HIF-1α signaling, contributing to the regulation of EMT change, migration, and invasion induced by hypoxia in androgen-independent prostate cancer cells." (PMID 32215176, 2020). "Moreover, suppression of TRPM7 abrogated HIF-1α/Annexin A1 signaling pathway to reduce hypoxia-induced EMT, cell migration, and invasion of androgen-independent prostate cancer cells." (PMID 32215176, 2020). "Negative ANXA1 expression was also a poor prognostic indicator in pancreatic ductal adenocarcinoma, and showed a direct role in enhancing tumor aggressiveness in prostate cancer." (PMID 29091952, 2017). "Furthermore, hypoxia was shown to increase the expression of Annexin A1 (ANXA1), which induces prostate cancer cell proliferation." (PMID 28614714, 2017). "Recent studies provide evidence linking ANXA1 as an endogenous inhibitor of NF-κB that can be induced by glucocorticoids and modified nonsteroidal anti-inflammatory drugs (NSAIDs) in colon and prostate cancer cells." (PMID 29263330, 2017). "Yet, in prostate cancer, the involvement of AnxA1 in this pathway was not by an antiproliferative but rather a proapoptotic action through p38 and JNK (c-Jun N-terminal kinase) activation." (PMID 24719523, 2014). "Recently, it was reported that hypoxia stimulus increased Annexin A1 protein expression, and thus to accelerate cell invasion and aggressiveness of prostate cancer cell, implying that HIF-1α/Annexin A1 signaling played a crucial role in hypoxia-regulated metastasis of prostate cancer." (PMID 32215176, 2020). "Furthermore, both TRPM7 and HIF-1α knockdown significantly suppressed hypoxia-induced Annexin A1 protein expression, and suppression of HIF-1α/Annexin A1 signaling significantly inhibited hypoxia-induced cell migration and invasion of androgen-independent prostate cancer cells." (PMID 32215176, 2020).
glioma (39 papers, 2013 to 2025). A benign or malignant brain and spinal cord tumor that arises from glial cells (astrocytes, oligodendrocytes, ependymal cells). "Other notable signals included IL6, VEGFA, TGFB1, and ANXA1, genes associated with mesenchymal transition, angiogenic niches, and poor prognosis in glioma." (PMID 41514565, 2025). "ANXA1 has been implicated in promoting treatment resistance and immunosuppressive microenvironment formation in glioma." (PMID 40583858, 2025). "TCGA database analysis further revealed a strong positive correlation between NFE2L2 (the gene encoding NRF2) and CD44, TNFRSF1A, and ANXA1 expression in glioma tissues." (PMID 40583858, 2025). "This dramatic OS reduction is thought to be associated to an immune downregulation induced by ANXA1, favouring the inhibitory glioma microenvironment." (PMID 39570467, 2024). "Another study revealed that ANXA1 expression was elevated in glioma tissues compared to normal tissues, and higher ANXA1 expression was associated with poorer prognosis in glioma patients." (PMID 38639785, 2024). "The purpose of mutation analysis is to better identify the mutation status and sites of ANXA1 in glioma, and mutation sites are common targets of gene therapy." (PMID 34422796, 2021). "Taken together, glioma subtypes classified by ANXA1 expression showed distinct mutation and CNA features." (PMID 34912807, 2021). "The evaluation of the association between clinicopathological features and the ANXA1 gene was conducted for 1,018 glioma patients from a Chinese cohort." (PMID 34912807, 2021). "Based on transcriptome sequencing analysis of the glioma samples from TCGA database, we found that increased ANXA1 expression was significantly associated with advanced clinicopathological features and poor prognosis in patients with glioma." (PMID 34422796, 2021). "In summary, ANXA1 correlates with immune-related function and cancer hallmark and plays a critical role in the glioma ecosystem." (PMID 34912807, 2021). "There was a reduced expression of ANXA1 in glioma with IDH mutation based on LGGs and GBMs (all p < 5e-9)." (PMID 34912807, 2021). "In our current study, we elaborated the functions of ANXA1 in gliomas from different datasets, including gene mutations, CNAs, and transcriptomic RNA sequences, especially at the single-cell transcriptomic level." (PMID 34912807, 2021). "To further investigate the role of ANXA1 expression in glioma, we performed differential expression and mutation analyses of ANXA1 using GEPIA (gepia.cancer-pku.cn) and cBioPortal (see text footnote 4) databases." (PMID 34422796, 2021). "Conversely, reduced ANXA1 expression has been associated with enhanced apoptosis in glioma cells." (PMID 41283264, 2025). "The findings suggest that ANXA1 overexpression is linked to a worse prognosis in glioma patients and that ANXA1 could serve as a potential therapeutic target for the treatment of gliomas." (PMID 38639785, 2024). "In gliomas, ANXA1 expression significantly increased in poorly differentiated human primary gliomas compared with normal brain tissue or lower‐grade tumours, indicating that ANXA1 is associated with the development and progression of malignant glioma." (PMID 35770335, 2022). "Some studies in gliomas have shown that ANXA1 is a risk prognostic factor Therefore, we investigated the expression, prognosis, and related mechanisms of ANXA1 using a public database to provide new markers and potential therapeutic targets for glioma patients." (PMID 35711921, 2022). "In addition, we analysed the clinical significance of ANXA1 and found its expression to be an independent risk factor for glioma." (PMID 35415239, 2022). "As we know, the MGMT promoter methylated status has a confirmed association with TMZ therapy in GBMs; thus, we imply that ANXA1 not only functions as an important factor of the post-surgery recurrence of glioma but also results in the resistance of TMZ chemotherapy." (PMID 34912807, 2021).
glioma (continued). "Furthermore, the mutational profile revealed that glioma subtypes classified by ANXA1 expression showed distinct genetic features." (PMID 34912807, 2021). "Anxa1 expression seemed to be crucially regulated by FoxM1 through direct interaction with Anxa1 promoter, as mutation of the FoxM1 binding site significantly reduced Anxa1 promoter activity in glioma cells." (PMID 23991102, 2013). "Moreover, increased expression level of ANXA1 in gliomas was associated with worse prognosis." (PMID 38347462, 2024). "GSEA showed that the coexpressed positive genes associated with ANXA1 were mainly involved in immune-related functions, such as interferon-gamma response and regulation of innate immune response, suggesting a regulatory role in the immune microenvironment in gliomas." (PMID 34912807, 2021). "We constructed the NRF2 gene regulatory network in glioma cells using single‐cell RNA sequencing data and identified ANXA1 as a downstream NRF2 target gene." (PMID 40583858, 2025). "The knockdown of originally high ANXA1 expression has been assessed previously in cancer cell lines, showing suppressive effects on the viability and proliferation of glioma cells and squamous cell lung cancer cells." (PMID 40361334, 2025). "Similar results were reported in glioma; papillary thyroid cancer; and breast, pancreatic, ovarian, and colorectal ANXA1-expressing cancer cell lines." (PMID 40361334, 2025). "Specifically, ANXA1 released from glioma cells can induce the M2 phenotype in macrophages by binding to the macrophage FPR1 receptor." (PMID 40583858, 2025). "Hypoxia activation of the HIF1A‐FOSL2 axis in glioma cells upregulates ANXA1 recruitment and induces the transformation of monocytes into M2‐like macrophages." (PMID 40583858, 2025). "The mechanisms by which ANXA1 affects macrophage polarization in gliomas and other cancers have been well‐established in recent years." (PMID 40583858, 2025). "Analysis of TCGA, CGGA, and Rembrandt datasets revealed that high ANXA1 expression predicted poor prognosis in glioma patients." (PMID 40583858, 2025). "The violin plot demonstrated that IGFBP2, SMC4, PLAT, and ANXA1, showed relatively higher expression levels in pericytes and glioma cells compared to other scoring genes." (PMID 39906742, 2024). "Because the present study was based on online databases and glioma tissue samples, there were several limitations, indicating that additional clinical experimental studies are needed to improve the reliability of ANXA1 in glioma research." (PMID 35711921, 2022). "Changes in tumour necrosis factor receptor 1 (TNFR1) and ANXA1 expression in glioma cells stimulated with TNF-α were revealed through western blot analysis and immunofluorescence staining." (PMID 35415239, 2022). "All these results indicate that ANXA1 contributes to glioma cell proliferation upon TNF-α stimulation." (PMID 35415239, 2022). "K–M curves and log-rank tests suggested that higher ANXA1 expression indicates poorer survival in glioma." (PMID 35415239, 2022). "Our experiments identified that expression of TNFR1 and ANXA1 is altered in glioma cells stimulated with TNF-α." (PMID 35415239, 2022). "It is worthy to note that, based on the immunohistochemical staining of two tissue microarrays, results verified again that average ANXA1 immunostaining scores were significantly higher in GBM than in low‐grade gliomas (LGG) or normal tissues." (PMID 35770335, 2022). "According to data analysis, ANXA1 is a potential prognostic factor of gliomas, consistent with the literature." (PMID 35415239, 2022). "In our study, we analyzed the expression of ANXA1 in glioma through the GEO database, which demonstrated that ANXA1 was highly expressed in glioma patients." (PMID 35711921, 2022). "FoxM1, a well-studied transcription factor, increases ANXA1 expression and promotes the proliferation, invasion, and angiogenesis of glioma." (PMID 35415239, 2022).
glioma (continued). "From the results of the χ2 test, ANXA1 expression differed in glioma specimens with different WHO grades." (PMID 35415239, 2022). "The independent prognosis analysis showed that the ANXA1 gene was an independent prognostic factor of glioma." (PMID 35711921, 2022). "Based on the expression data for gliomas and normal tissues in the GSE4290, GSE7696, GSE29796, and GSE50161 datasets, the ANXA1 gene was significantly highly expressed in gliomas, and the results were verified by GEPIA and Human Protein Atlas online analyses." (PMID 35711921, 2022). "Together, these results suggest that high ANXA1 expressions are correlated with glioma aggressiveness." (PMID 35770335, 2022). "Blocking the overexpression of the ANXA1 gene is likely to improve the prognosis of glioma patients." (PMID 35711921, 2022). "Using immunohistochemistry with tissue microarrays, we showed that ANXA1 was overexpressed in GBM, positively correlated with higher World Health Organization (WHO) grades of glioma, and negatively associated with poor survival." (PMID 35770335, 2022). "In summary, our results indicate that the TNF-α/TNFR1/ANXA1 axis regulates the proliferation of glioma cells and that ANXA1 plays a regulatory role in the inflammatory microenvironment." (PMID 35415239, 2022). "TNF-α is involved in activation of the NF-kB and PI3K-Akt signalling pathways, and ANXA1 regulates the proliferation, migration, and invasion of glioma cells via PI3K/AKT signalling." (PMID 35415239, 2022). "To further explore ANXA1’s role in the tumor environment, we collected single-cell transcriptomic data in gliomas from a previous study." (PMID 34912807, 2021). "In this study, we integrated bulk genomic and transcriptomic profiles and scRNA-seq data to comprehensively characterize ANXA1’s role in gliomas." (PMID 34912807, 2021). "According to ANXA1 expression, gliomas were divided into G1 group (low expression, n = 116) and G2 group (high expression, n = 115)." (PMID 34912807, 2021). "For Glioma tissue samples we screened several known biomarker proteins including ANXA1, SOD2 and VIM." (PMID 34055594, 2021). "Consistently, the immunohistochemistry (IHC) experiments of glioma patients (WHO II–IV grade) showed that ANXA1 was the highest in WHO IV patients and lowest in WHO II patients (all p < 0.05)." (PMID 34912807, 2021). "Gliomas with high expression levels of ANXA1 showed a significant poor prognosis for overall survival (OS) in both gliomas and LGGs (log-rank test, p < 1.0e-4)." (PMID 34912807, 2021). "To explore ANXA1’s role in gliomas, we examined its transcriptomic level in different subtypes of gliomas in two batches of RNA-seq data from the CGGA database." (PMID 34912807, 2021). "In summary, these findings have proposed that ANXA1, a key gene in glioma, in moving the tumor cell and glioma inhibitory microenvironment, can be a promising direction for the therapeutic strategy in gliomas." (PMID 34912807, 2021). "Previously, several studies have reported the expressing pattern and function of HIST1H2BK and ANXA1 in glioma." (PMID 34976054, 2021). "Recent findings further demonstrated that AnxA1 regulates proliferation, migration, and invasion of the glioma cells via the PI3K/Akt signaling pathway." (PMID 34650406, 2021). "To further explore the role of the ANXA1 gene in clinical application, we examined the prognostic value in all kinds of subtypes in gliomas." (PMID 34912807, 2021). "As ANXA1 confers an extended immune status, we sought to further explore the ANXA1 regulatory immune role in the glioma ecosystem." (PMID 34912807, 2021). "For instance, knockdown of ANXA1 was reported to suppress the proliferation and metastasis of glioma cells via regulating the PI3K/Akt signaling pathway." (PMID 34976054, 2021). "The mutation type of ANXA1 in GBM was mainly amplification, while in low-grade gliomas was mainly mutation." (PMID 34422796, 2021).
glioma (continued). "ANXA1 was found to be upregulated in Glioma tissues (peptides GLGTDEDTLIEILASR, GVDEATIIDILTK and GTDVNVFNTILTTR)." (PMID 34055594, 2021). "To explore the exhaustive function of ANXA1 in gliomas, we integrated the bulk genomic and transcriptomic profiles and scRNA-seq data to comprehensively characterize the role of ANXA1 in gliomas." (PMID 34912807, 2021). "For genes in interferon-gamma response, we confirmed that they are associated with ANXA1 expression, and show the differential expressed patterns in glioma subtypes grouped by ANXA1 expression." (PMID 34912807, 2021). "Overexpression of ANXA1 was observed in astrocytoma in the immunohistochemical analysis; whereas, its prognostic value in glioma patients was reported in a previous cross-validated model study." (PMID 33425732, 2020). "ANXA1 was observed overexpressing in patients with gliomas, hepatocellular carcinoma, and adenocarcinomas of pancreas and esophagus." (PMID 33291071, 2020). "Up-regulated ANXA1 expression was correlated with tumour progression in urothelial carcinoma, glioma, colon carcinoma and lung squamous carcinoma, whereas down-regulated ANXA1 expression was observed in prostate, oral and gastric cancer progression." (PMID 25510623, 2014). "To determine the effect of increased FoxM1 expression on Anxa1 expression, we studies two human glioma cell lines, Hs683and SW1088, that had low levels of the FoxM1 expression." (PMID 23991102, 2013). "Overexpression of FoxM1 up-regulated Anxa1 expression, whereas suppression of FoxM1 expression down-regulated Anxa1 expression in glioma cells." (PMID 23991102, 2013). "Consistent with previous studies, we found that mRNA and protein levels of FoxM1 and Anxa1 were up-regulated in human glioma specimens and related to the poor outcome." (PMID 23991102, 2013). "In conclusion, we found that FoxM1 directly regulated Anxa1 expression to promote glioma cells proliferation, migration, and angiogenesis." (PMID 23991102, 2013). "In the present study, we identified both FoxM1 and Anxa1 are overexpression in the primary glioma specimens, and predicts poor survival." (PMID 23991102, 2013). "In the present study, we show that Anxa1 was overexpression in gliomas and predicted the poor outcome." (PMID 23991102, 2013). "Our findings provide both clinical and mechanistic evidences that FoxM1 contributes to glioma development by directly up-regulating Anxa1 expression." (PMID 23991102, 2013). "In the present study, we show that Anxa1 expression related to FoxM1 expression in human glioma tissues and predict poor outcome." (PMID 23991102, 2013). "Consistent with their studies, we showed that Anxa1 mRNA and protein expressions were up-regulated in glioma specimens and related to the poor outcome." (PMID 23991102, 2013). "Next, we tested the function of FoxM1/Anxa1 interaction by assessing their roles in glioma cells biological behaviors." (PMID 23991102, 2013). "To provide direct evidence that FoxM1 affect the angiogenic phenotype by regulating Anxa1 of glioma cells, we determined the angiogenic ability of the U-87MG-RNAi-Anxa1 and SW1088-FoxM1-RNAi cells using an endothelial cell tube formation assay." (PMID 23991102, 2013). "Together, our results indicate that FoxM1 enhances the angiogenic ability of glioma cells by up-regulating the Anxa1 expression." (PMID 23991102, 2013). "We observed a significant correlation between FoxM1 and Anxa1 expression in glioma cells and provide evidence that FoxM1 promote glioma proliferation, migration, and angiogenesis by up-regulating Anxa1 expression." (PMID 23991102, 2013). "To determine the FoxM1 and Anxa1 expression levels in glioma cells lines, we examined the FoxM1 and Anxa1 expression in Hs683, SW1088, LN-229, and U-87MG cell lines by RT-qPCR and Western blot." (PMID 23991102, 2013). "Additionally, another study found that ANXA1 plays a significant role in the proliferation of glioma cells stimulated by TNF-α." (PMID 38639785, 2024).